SOX9 (SRY-box transcription factor 9)
Diseases named in the same sentence as SOX9 in open-access papers (continued):
Sharing a sentence is not in itself a finding about the gene and the disease.
cancer (continued). "Analysis revealed that genes associated with cancer stem cells, such as POU5F1 (OCT4), SOX2, NANOG, BMI1, BMP2, CD44, SOX9, and ALDH1 were markedly upregulated in enzalutamide resistant cells." (PMID 33339129, 2020). "In this way, mmu_circ_0000730 maintains a high level of SOX9 and promotes the stemness of cancer stem cell and EMT by titrating the function of mmu-miR-466i-3p and mmu-miR-466 f-3p." (PMID 32686598, 2020). "As a member of SOX family, SRY-box transcription factor 9 (SOX9) can regulate cancer progression by affecting the transcription of diverse genes." (PMID 33318478, 2020). "In various cancer types, SOX9 has been observed to be deregulated because of the amplification and other mechanisms." (PMID 33318478, 2020). "Gli1, LSD1, Sox9 were primarily expressed in the nucleus of cancer cells; CD44 primarily located in the membranes of cancer cells." (PMID 32430068, 2020). "SOX9 also plays an important role in cancer, and SOX9 inhibition remarkably suppressed the proliferation, migration and invasion of NSCLC cells." (PMID 32206066, 2020). "Our results revealed a marked and significant decrease in mitotic cells in SOX9-silenced cancer cells respect to cells transduced with empty vector." (PMID 31941916, 2020). "It has been shown that nuclear MET (nMET) can regulate nuclear Ca2+ or YAP signaling to stimulate cell proliferation or induce SOX9 and β-catenin to enhance cancer stem-like cells’ self-renewal for cancer recurrence." (PMID 30700325, 2019). "Understanding the functional roles of SOX9 and clinical relevance is crucial for developing novel treatments targeting CSCs in cancer." (PMID 31057614, 2019). "In this review we aim to condense the knowledge about the involvement of SOX9 in the initiation and progression of different types of cancer and to highlight its potential as a clinical biomarker." (PMID 31057614, 2019). "Several studies in different types of cancer showed the connection between SOX9 and the Wnt/β-catenin." (PMID 31817513, 2019). "SOX9 has been identified to drive Wnt/β-catenin signaling pathway activation and cancer progression." (PMID 30658681, 2019). "Currently, there is enough evidence suggesting an oncogenic role for SOX9 in different types of human cancers." (PMID 31057614, 2019). "Nuclear enriched abundant transcript 1 (NEAT1) is a long non-coding RNA (lncRNA) located on chromosome 11 whose abnormal expression has been identified in a number of cancers and is involved in the miR-101-3p/SOX9/Wnt/β-catenin axis." (PMID 31817513, 2019). "It has been reported that the upregulation of transcription factor SOX9 in ER+ recurrent cancer is sufficient for tamoxifen resistance." (PMID 31690832, 2019). "This is specially required for gaining a better understanding of SOX9 roles in normal and disease states to developing novel cancer therapeutic strategies." (PMID 31057614, 2019). "GLI1 directly induced the transcription of SOX9 and a positive feedback promoting SOX9-dependent cancer stem cell properties was observed." (PMID 31057614, 2019). "Deletion or silencing of Sox9 in cancer cells led to a clear change in cell morphology, from a characteristic spindle-like morphology to a cobblestone-like monolayer." (PMID 30622340, 2019). "SOX9 upregulation is common in colorectal adenoma and cancer and is an independent indicator for an adverse prognosis in CRC." (PMID 31057614, 2019). "In HCC, the loss of HNF4 and expression of the cancer stem cell (CSC) markers CD44, CK19, Sox9, and EpCAM are considered to be indicators for poor prognosis." (PMID 31726709, 2019). "Mechanistically, Sox9 acts downstream of Sox2 to control luminal progenitor cell content and is required for expression of the cancer stem cell marker ALDH1A3 and Wnt signalling activity." (PMID 30622340, 2019). "This review provides a summary of the current knowledge about the involvement of SOX9 in development and progression of cancer." (PMID 31057614, 2019).
cancer (continued). "Gastrokine 1 (GKN1), a tumor suppressor like protein which expression is lost in gastric tumors (including adenoma and cancer), was responsible for decreased SOX9 expression in AGS and MKN-1 cells." (PMID 31057614, 2019). "It is already known that SOX9 has an adaptable role since it participates in different steps of cancer progression." (PMID 31057614, 2019). "Considering the versatile functions of SOX9 in cancer biology, further research such as expression profile and proteomic analysis will be conducted to explore the entire mechanism framework of SOX9 on the regulation of cancer stemness in the future." (PMID 29416606, 2018). "SOX9 is a SRY-related gene known for chondrogenesis and the development of the male gonad, and more and more studies about the ectopic expression of SOX9 and its influence on the progress of carcinogenesis have been reported in several human cancers." (PMID 29587675, 2018). "Sex-determining region Y-box (SRY-box) containing gene 9 (SOX9) expression confers cancer stem cell features." (PMID 30420613, 2018). "These study shows that Sox9 dysfunction contributes to miR-133b biological functions, especially in cancer progression." (PMID 29970901, 2018). "The transcription factor SOX9 has been shown to be a key regulator in various processes during embryogenesis, stem cell commitment and cancer." (PMID 29484136, 2018). "SOX9 has roles in epithelial invasion, migration, and proliferation and plays important roles in multiple types of cancers." (PMID 29416606, 2018). "Knockdown of SOX9 in both iCCA and eCCA cells remarkably inhibited the capacity of cancer cell proliferation and migration, decreased CSC stemness and increased apoptosis." (PMID 30420613, 2018). "We also observed a high frequency of chromosomal losses in two other significantly mutated known cancer genes: SMAD4 (n = 46) and SOX9 (n = 44)." (PMID 29522538, 2018). "Controls showed significantly reduced SOX9 expression compared to nodal positive carcinomas (59% vs. 85% high SOX9 expression; p = 0.006)." (PMID 29703178, 2018). "Another group also reported that miR-140/SOX2/SOX9 axis regulates cancer stem cells in early breast cancer." (PMID 29162923, 2017). "To further elucidate some possible cellular effects of SOX9 expression in HCC cancer cells, we used short interfering RNAs (siRNAs) to successfully knock-down the expression in HepG2 cells." (PMID 29121666, 2017). "By meta-analysis of the 17 studies, we identified the pool HRs which indicated that SOX9 was a factor in poor prognosis in various cancers." (PMID 29348895, 2017). "In cancer cells, Sox9 and Krüppel-like factor 4 (KLF4) interact with β-catenin and reduce its binding to TCF4 and showed anti-oncogenic activity by inhibiting the activity of the Wnt/β-catenin signaling pathway." (PMID 28279198, 2017). "Recent studies showed that SOX9 playing crucial roles in cancer cell proliferation, migration, angiogenesis and survival." (PMID 28147312, 2017). "Previously, SOX9 has been reported to activate Wnt signaling to promote cancer progression and the chemo-resistance of cancer cell." (PMID 29212230, 2017). "In this study, we provide the evidence that gankyrin expressed in myeloid cells promote the expansion of cancer-initiating cells through the induction of cancer stem cell markers such as Pim1 and Sox9." (PMID 28160571, 2017). "Together, these results suggest that SOX9 regulates cancer cell survival, consistent with our previous work in lung cancer." (PMID 28912540, 2017). "Taken together, these studies imply that linc-ROR and SOX9 are involved in stem/progenitor cell maintenance, but their roles in regulating cancer development remains to be explained." (PMID 29237490, 2017).
cancer (continued). "Most previous reports concerned with Sox9 functions on Wnt signaling are focused on cancer cells or embryonic cells." (PMID 28279198, 2017). "Further assays indicated that MALAT1 acted as a competing endogenous RNA to upregulate SOX9 expression by sponging miR-101 in DDP-resistant cancer cells, through Wnt signaling pathway." (PMID 29212230, 2017). "Since the first record on the analysis of SOX9 expression in human cancer published in 1997, more than hundreds studies have explored the role of SOX9 expression in tumors in larger patient groups." (PMID 29348895, 2017). "SOX9, another member of the SOX family, is overexpressed in COS and has been implicated in cancer progression." (PMID 28272374, 2017). "SOX9, one of the most widely-studied SOX family transcription factors, is also associated with the development of many human cancers." (PMID 29245941, 2017). "The top five up-regulated cancer stemness associated genes include: SNAI2 (SLUG) (8.2 folds), SOX9 (6.4 folds), ITGB3 (integrin β3) (5.4 folds), CD44 (4.3 folds) and MET (2.9 folds) (DU145FP vs. DU145WT)." (PMID 28698547, 2017). "The present meta-analysis was thus performed to highlight the link between dysregulated SOX9 expression and prognosis in cancer patients." (PMID 29348895, 2017). "The GABA-induced reduction in the expression of CD133, ALD-1, SHH, Gli-1 and SOX9 thus suggests significant inhibitory effects of GABA on cancer stem cells as contributing factors to the observed PDAC prevention in the current study." (PMID 27281617, 2016). "Here, we characterize the spectrum of SOX9 mutations, their molecular and clinical correlates, and their effect on SOX9 protein expression in comparison to SOX9 wild type (WT) carcinoma and normal epithelium within the context of CRC." (PMID 27248473, 2016). "Our study showed that SOX9 regulation of S100P promotes cancer cell migration and invasion as well as inducing EMT." (PMID 26009899, 2015). "Upregulation of SOX9 was reported to increase the capacity of cell proliferation, cell migration, and cell invasion in multiple types of cancer." (PMID 26317788, 2015). "The fraction of cancers with detectable SOX9 expression in this study was 67%, including 51% with moderate to strong staining." (PMID 26030748, 2015). "PTEN deletions were positively associated with SOX9 expression in ERG-negative (p<0.0001) but inversely linked to SOX9 expression in ERG-positive cancers (p<0.0001)." (PMID 26030748, 2015). "This analysis revealed, that a loss of SOX9 expression was strongly linked to PSA recurrence in PTEN-deleted cancers (p = 0.008) but only weakly in cancers with normal PTEN copy numbers (p = 0.02)." (PMID 26030748, 2015). "Deregulation of SOX9 has been reported for several cancers, including CRC, and recent large-scale exome-sequencing efforts have revealed that SOX9 is mutated in a subset of CRCs." (PMID 24904831, 2014). "SOX9 is another example of an oncogenic SOX protein that is overexpressed in multiple cancer types including colorectal, glioma, and pancreatic cancers." (PMID 25594027, 2014). "Over the past 5 years, it has become increasingly clear that Sox9 plays a major role across numerous human cancers." (PMID 25004243, 2014). "Some of the upregulated genes are related to CSC/’cancer stemness’ such as CXCR4, CD133, EPCAM and SOX9, while others are associated with apoptosis (FASLG, TJP2, DUSP4), the MAPK pathway (MAP2K4, DUSP4), and chemoresistance (MMP1, an ETS1 target gene)." (PMID 24069258, 2013). "Given the roles of Sox9 in development and cancer we sought to identify a Sox9-dependent transcriptome." (PMID 22761195, 2012). "This transcription factor has been recently identified as having an importat role during embryogenesis and in the early stages of prostate development and in testis determination, processes that link SOX9 upregulation to cancer development." (PMID 20805891, 2010).
cancer (continued). "Among the genes showing twofold hypermethylation in at least 7 of 10 cancers, SOX9 gene was chosen for further analysis." (PMID 18087279, 2008). "It was noteworthy that SOX9 was upregulated in most cancers and expressed in all 6 cell lines, in accordance with that of β-catenin." (PMID 16504081, 2006). "Though the results obtained do not support using SOX9 as a diagnostic or prognostic marker in cancer, additional studies using other biological models are needed." (PMID 40141294, 2025). "The alterations in biochemical pathways in cancer cells upon suppression of SOX9 expression was investigated based on the expression levels of transcripts involved in each pathway using the Reactome online service (Pathway browser 3.7, database release 87, No interactors)." (PMID 40141294, 2025). "Moreover, extensive evidence underscores that SOX9 drives drug resistance by regulating pro-survival signaling pathways and stemness properties across multiple cancers." (PMID 40240356, 2025). "Nevertheless, we hope that the results obtained by us may stimulate deeper research on SOX9 role in drug resistance of cancer." (PMID 40141294, 2025). "Sox4, Sox9, and Sox17 may play roles in cancer progression and metastasis in hepatocellular carcinoma." (PMID 40980324, 2025). "The relevance of our mouse model findings is reflected by marked reduction or loss of SOX9 protein expression in approximately 20% of primary CRCs, and the subset of patients with CRC whose cancers show marked reduction in SOX9 gene expression have poor prognosis." (PMID 40179020, 2025). "In this study, we provide evidence supporting the hypothesis that SOX9 drives chemoresistance in HGSOC by reprogramming the transcriptional program of naive OC cells into stem-like cancer cells." (PMID 41031891, 2025). "In addition, elevated SOX9 expression favors the development of therapy resistance in various cancers, consequently leading to unfavorable prognostic outcomes." (PMID 40240356, 2025). "This makes SOX9 inhibition a compelling strategy to improve cancer immunotherapy." (PMID 41293317, 2025). "Overall, these data not only further confirm the nuclear import of YAP via its direct interaction with SOX9 but also provide compelling evidence that disruption of SOX9-partner interactions represents a valuable approach with potential application for cancer therapy." (PMID 38653754, 2024). "SOX2 and SOX9 are often deregulated in cancer and a dual role was described for both TFs." (PMID 38275880, 2024). "Malignant cancer cells were defined by high expression of Afp, Sox9 and Epcam." (PMID 38317186, 2024). "Organoid formation from testicular tissue collected from childhood cancer patients positively correlates with SRY-Box transcription factor 9 (SOX9) expression in Sertoli cells, which in turn negatively correlates with previous exposure to alkylating chemotherapy." (PMID 39188568, 2024). "Thus, mmu_circ_0000730 targets mmu-miR-466i-3p and inhibits cancer progression by decreasing SOX9 expression and blocking the STAT3 signaling pathway." (PMID 38192436, 2024). "Immunofluorescence (IF) coexpression of HIF1A and SOX9 (n = 3, sourced from the National Cancer Center) confirmed our hypothesis to some extent." (PMID 39033089, 2024). "Moreover, pan‐cancer expression analysis of the TCGA and CCLE datasets revealed that GBC ranked among the top cancer types in terms of SOX9 and TCF7L2 mRNA levels." (PMID 39492805, 2024). "Indeed, multiple studies have suggested an inverse correlation between the expression of SOX2 and SOX9 in cancer in a context dependent manner." (PMID 38275880, 2024). "In addition, studies have shown that SOX9 can be negatively regulated by microRNAs and regulate the development of cancer." (PMID 37328795, 2023). "Subsequently, the role of SOX9 in cancer growth and invasion was revealed." (PMID 37020558, 2023).
cancer (continued). "What’s more, transwell and wound healing assays revealed that up-regulated SOX9 level could reverse the restrain of cancer cells migration and invasion brought by silencing HCG18." (PMID 36854894, 2023). "The requirement of SOX9 for proliferation in these cell types has led to the idea that a “critical dose” of SOX9 may be important for intestinal stem and cancer cell proliferation." (PMID 36423688, 2023). "Indeed, NFκB has been shown to positively regulate SOX9 expression with the NFκB binding sites found within the SOX9 promoter in cancer stem cells." (PMID 37997980, 2023). "SOX9 has been shown to be related to the metastasis of various cancers." (PMID 37919693, 2023). "In addition, we detected the relevance between the state of immune invasion and SOX9 expression in cancer." (PMID 37020558, 2023). "Altogether, SOX9 could be a biomarker for diagnostics and prognostics for pan-cancers and an emerging target for the development of anticancer drugs." (PMID 37020558, 2023). "Similarly, a subpopulation with overexpressed cancer stem cell markers SOX9 was discovered in the single cells derived from one T3-stage MIBC." (PMID 36902193, 2023). "Nuclear SOX9 expression was used to identify WNT-high cancer cells." (PMID 37309673, 2023). "Next, we explored the immunomodulatory role of SOX9 in cancer." (PMID 37020558, 2023). "Thus, circ-PHC3 appears to exert effects on cancer stem cell differentiation through regulation of the miR-497-5p/SOX9 axis." (PMID 37468993, 2023). "Furthermore, SOX9, SOX10, and SOX11 are associated with increased tumor metastasis and worse overall survival by regulating the ability of cancer cells to undergo EMT and acquire mesenchymal characteristics." (PMID 37444447, 2023). "Interestingly, latent competent cancer cells expressing SOX2/SOX9 increase dormant CSCs (or latency-competent cancer cells) that downregulate NKG2DL through a unique mechanism that produces the WNT inhibitor DKK1, thus evading NK cell-mediated immunity." (PMID 37394580, 2023). "Through CCK-8, EdU and colony formation assays, we found that increasing SOX9 level in si-HCG18-1 and SOX9 ov co-transfection group could facilitate cancer cell proliferation when compared to si-HCG18-1 group." (PMID 36854894, 2023). "SOX9 has been recognized for its oncogenic potency in several cancers." (PMID 37291545, 2023). "Over the past decade, SOX9 has been intensively studied in the field of cancer." (PMID 37020558, 2023). "However, an upregulation of cancer stemness markers such as SOX9, CD44, and CD9 implies that GBM is potentially moving towards cancer-specific stemness in the presence of NSCs." (PMID 36834653, 2023). "Furthermore, through corresponding functional assays, indicated that SOX9 was an oncogene, overexpression of SOX9 altered the inhibition of cancer cell promotion mediated by lncRNA HCG18 knockdown through PI3K/AKT pathway." (PMID 36854894, 2023). "However, the expression and immunomodulation of SOX9 in pan-cancer and the regulation of the small-molecule drug CD in cancer cell lines are not clear." (PMID 37020558, 2023). "The role of SOX9 in cancer has prompted interest in developing SOX9 inhibitors, which could be leveraged for the treatment of PF." (PMID 37510994, 2023). "In several carcinomas, SOX9 is also known to have important functions." (PMID 38002064, 2023). "Furthermore, SOX9 signaling or SOX9 controlled signaling pathways play an important role in cancer development and metastasis." (PMID 36303551, 2022). "In the study described, exosomes acted in a way similar to the mechanisms previously indicated by other authors: sensitive cancer cells became resistant to oxaliplatin by accumulating exosomes with high circ_0032821 expression and by actively regulating the miR-515-5p/SOX9 axis." (PMID 36139487, 2022).